ITIH4 (inter-alpha-trypsin inhibitor heavy chain 4)
Diseases named in the same sentence as ITIH4 in open-access papers (continued):
Sharing a sentence is not in itself a finding about the gene and the disease.
schistosomiasis (1 paper, 2022). An infectious disease caused by parasitic trematodes of the genus Schistosoma that colonize human blood vessels and release eggs that can cause granulomatous reactions leading to acute (swimmer's itch or acute schistosomiasis syndrome) or chronic disease. "Our analyses also indicated that ITIH4, PMEPA1, and MAMSTR are potentially causal genes affecting the severity of schistosomiasis." (PMID 35493725, 2022).
steatosis (1 paper, 2019). Increased lipid within the cytoplasm of cells. "Among those proteins, inter-alpha-trypsin inhibitor heavy chain 4 (ITIH4) plays an important role in predicting the course of NAFLD over time, from simple steatosis to NASH and HCC." (PMID 31238892, 2019).
stomach adenocarcinoma (1 paper, 2021). "For example, ITIH1 and ITIH4 were more highly expressed in stomach adenocarcinoma (STAD) and kidney renal clear cell carcinoma (KIRC) as compared with the normal tissues." (PMID 33744857, 2021).
syphilis (1 paper, 2024). A contagious bacterial infection caused by the spirochete Treponema pallidum. "Using multicenter ELISA validations, we selected three biomarkers (SEMA7A, SERPINA3, and ITIH4) and confirmed their efficacy in distinguishing NS from syphilis and other brain diseases, including infectious diseases." (PMID 38380496, 2024).
thyrotoxicosis (1 paper, 2022). A hypermetabolic syndrome caused by the elevation of thyroid hormone levels in the serum. "In the present study, Itih1, Itih2, Itih3, and Itih4 were downregulated in thyrotoxicosis mice, which also reflected the decline of defense and protective capability." (PMID 35720307, 2022).
type 2 diabetes (1 paper, 2023). "Genetic variants in or near the CDKAL1, KLF9, GP2, ALDH2, and ITIH4 genes are associated with obesity and genetic variants in or near the GDAP1, PTF1A, SIX3, ALDH2, and PAX4 genes are specifically associated with type 2 diabetes in East Asians." (PMID 37749090, 2023).
infection (370 papers, 2004 to 2026). The state of being infected such as from the introduction of a foreign agent such as serum, vaccine, antigenic substance or organism. "Among the common proteins that were increased in abundance, all (Saa1, Lrg1, Hpx, Hp, Itih4, Serpina3n, Fga/b/g, Cp, and C3) were associated with the acute-phase response to infection." (PMID 32843537, 2020). "As an acute phase response protein, ITIH4 is increased in response to infection and inflammation, and may provide important diagnostic information during surgical trauma." (PMID 36304541, 2022). "Interestingly, significantly elevated expression of six above-mentioned associated genes (Pmepa1, Mamstr, Rasip1, Tpm1, Itih4 and Ogdhl) in mice total liver tissues was also observed from the seventh week (S. japonicum spawn in large numbers) after infection." (PMID 35493725, 2022). "The up-regulated expression of COL1A1 and ITIH4 in the mastitic mammary gland may be associated with tissue damage and repair during late stages of infection." (PMID 25273983, 2014). "We focused on ITIH4 and IgM proteins since lectin blotting and LC-MS/MS proteomic analysis indicated that they were impacted by infection." (PMID 30918063, 2019). "In this study, however, at the late stage of infection, the ITIH4 protein was first found to be significantly increased in the mammary gland tissues as compared to the control case." (PMID 25273983, 2014). "In this study, ITIH1, ITIH2, were found to be negative acute phase reactants while ITIH3, and ITIH4 acted as positive acute phase proteins during both infection types in NHPs." (PMID 30774579, 2019).
cancer (41 papers, 2008 to 2025). A tumor composed of atypical neoplastic, often pleomorphic cells that invade other tissues. "Among them, TIMP1, LGALS3BP, A2M, AHSG, FN1, HRG, and ITIH4 have been associated with cancer, while CF I, C2, and C4A, have been related to complement activity." (PMID 37685286, 2023). "Accumulated data from previous studies appear to suggest a link between the overexpression of a 35 kDa fragment of serum inter-alpha-trypsin inhibitor H4 (ITIH4) with cancers that are associated with up-regulated levels of oestrogens." (PMID 24252421, 2013). "The idea that the abundance of the ITIH4 fragment is linked to high amounts of serum kallikreins is derived from previous reports demonstrating overexpression of members of the kallikrein family in cancers of the breast, ovary and endometrium." (PMID 24252421, 2013). "Interestingly, these and other fragments of ITIH4 have previously been found to be up or downregulated in the serum of patients with various cancers and this is believed to arise from disease associated alterations in protease activity." (PMID 19550422, 2009). "ITIH4 is more controversial, with some studies demonstrating up‐ and downregulation in various cancers and stages of disease." (PMID 39660530, 2024). "IPA analysis indicated that pathways of LXR/RXR activation and FXR/RXR activation were most significantly activated, in which APOH, CLU, and ITIH4 were involved in cancer, organismal injury and abnormalities, and reproductive system disease." (PMID 33299887, 2020). "The significance of ITIH4 was further confirmed by immunohistochemistry of pig liver specimens, showing that it is synthesized in both cancer lesions and the parenchyma in advanced NAFLD." (PMID 31238892, 2019). "We have previously analyzed the expression of the 35 kDa ITIH4 fragment in groups of patients with nine different types/subtypes of cancers using the gel-based proteomics approach and a lectin that binds to O-glycosylated proteins." (PMID 24252421, 2013). "ITIH4 is a protein involved in acute phase reaction and is considered to be a possible marker of cancer." (PMID 22568928, 2012). "In addition, SERPINC1, APOA4, APOE and ITIH4 are described deviated in the serum of hyperplasia or cancer patients by two teams." (PMID 37091170, 2023). "Furthermore, immunohistochemistry showed ITIH4 expression in hepatocytes also increased in both the cancer lesions and parenchyma as NAFLD progressed." (PMID 31238892, 2019). "The present lectin-based proteomic analyses were performed to assess the specificity of the 35 kDa fragment of ITIH4 as a potential cancer biomarker and determine whether it was also overexpressed in the sera of cancer-negative pregnant women who are known to have high levels of plasma oestrogens." (PMID 24252421, 2013). "In addition to the few cancer-related studies, ITIHs have also been reported to be involved in inflammatory diseases, such as rheumatoid arthritis and inflammatory bowel disease, and ITIH4 was shown to be an anti-inflammatory marker-protein in acute ischemic stroke." (PMID 33744857, 2021). "Western blotting data analysis confirmed the upregulation of CLU, ITIH4, SERPINC1, and C1RL in endometrial and exosome cancer sera compared to those of control subjects." (PMID 34298850, 2021). "Inter-alpha-trypsin inhibitor heavy chain H4 (ITIH4) is involved in acute phase reaction and has been found to be a possible cancer marker." (PMID 21975265, 2011). "Upregulation of 48 proteins in samples of cancer patients was reported, that included several inflammation/acute phase-related proteins: A1AG1 (ORM1), A1AT (SERPINA1), AACT (SERPINA3), CO4B, CO9, HPT, ITIH4, LBP and SAA1, which upregulation was revealed also in our study." (PMID 26376850, 2015).
cancer (continued). "Hence, these results, when taken together with the data of the previous studies, generally indicate that the overexpression of the 35 kDa ITIH4 fragment was not exclusive to oestrogen-related cancers but also occurs in normal pregnancy and benign conditions." (PMID 24252421, 2013). "Other proteins, such as CLEC3B, ITIH4, SAA1, and C20ORF3 exhibited increased expression in cancer EVs, while RBP4, SAA1, and DBP did not exhibit significant differences between normal and cancer samples." (PMID 33808296, 2021).
tumor (33 papers, 2008 to 2024). "Our results showed a favorable association between tumor-infiltrating immune cells and FN1, CXCL8, IL1β, and ITIH4." (PMID 38637796, 2024). "We also observed that the expression levels of ITIH1, ITIH3, and ITIH4 increased with tumor staging of KIRC patients, as did that of ITIH2 in KIRP patients." (PMID 33744857, 2021). "Significant alterations in Inter-alpha-trypsin inhibitor heavy chains (ITIH1, ITIH2, ITIH3, and ITIH4) levels were also observed due to their implication in tumor growth and the malignancy process." (PMID 32023884, 2020). "Our findings collectively support the utility of plasma ITIH3 and ITIH4 proteins as novel tumor biomarkers for diagnosis of CRC." (PMID 31481982, 2019). "In these mice, tumor formation was inhibited by downregulation of the IL-6 pathway by Itih4 deletion." (PMID 31238892, 2019). "Since tumor progression is tightly associated with re-arrangement of the extracellular matrix, employment of AMBP, ITIH1, and ITIH4 may also support the net benefit for early detection of CRC and designation of probable cell migration." (PMID 32023884, 2020). "S100A9 supports proliferation and metastasis in other tumor types; S100A9, hemopexin, and inter-alpha-trypsin inhibitor heavy chain H4 (ITIH4) were identified in saliva of patients with RCC and were suggested as potential biomarkers for disease screening." (PMID 34572331, 2021). "It is interesting to find that F2, ITIH4, and HPX proteins were mainly expressed in tumor cells of GBC tissues, but these proteins were located mainly in inflammatory cells of control tissues not normal gallbladder epithelium." (PMID 33718182, 2021). "Myeloperoxidase (MPO), complement C3, inter-alpha-trypsin inhibitor heavy chain H4 (ITIH4), apolipoprotein B-100 and kininogen-1 isoform 2 (KNG1) increased in the tumor group compared to the benign group." (PMID 32998289, 2020). "Therefore, we used the tumor IMmune Estimation Resource (TIMER) Web Server to investigate FN1, CXCL8, IL1β, and ITIH4's function in the Comprehensive Analysis of tumor-infiltrating Immune Cells." (PMID 38637796, 2024). "Although the expression levels of ITIH2, ITIH3, and ITIH4 also differed in different tumor stages of LIHC, the expression change directions were not always identical." (PMID 33744857, 2021).
cardiovascular disease (3 papers, 2014 to 2025). "We found 6 proteins that mediated the PGSCAD’s effect on MACE in EXSCEL (C9, LBP, ITIH4, APOM, CES1, and HS6ST2), providing supporting evidence that they might serve as biomarkers for cardiovascular disease in patients with T2D52–54." (PMID 40032831, 2025).
ITIH4 also shares sentences with these, for which no sentence is quoted: HIV-1 infection (185 papers); AIDS (55); influenza (21); neuroblastoma (12); neuropathy (12); dementia (8); Anxiety (7); neurological disorders (7); peripheral neuropathy (7); Immunodeficiency (6); infectious disease (6); astrocytoma (5); co-infection (5); encephalitis (5); prostate carcinoma (5); AIDS dementia (4); HIV-associated neurocognitive disorder (4); latent infection (4); lymphoma (4); memory impairment (4); Alzheimer disease (3); bipolar disorder (3); brain inflammation (3); malaria (3); neurodegenerative disease (3); Pain (3); pulmonary hypertension (3); Sensory neuropathy (3); Arrhythmia (2); Autoimmunity (2).
A further 99 diseases each share a sentence with ITIH4 in 2 papers or fewer.